KDM5B (lysine demethylase 5B)
Diseases named in the same sentence as KDM5B in open-access papers (continued):
Sharing a sentence is not in itself a finding about the gene and the disease.
tumor (continued). "Elevated levels of lysine demethylase 5B (KDM5B) have been found in a variety of human cancers, and it is considered to be a transcriptional suppressor associated with tumor growth, angiogenesis, invasion, metastasis, and tumor-related chemotherapy resistance." (PMID 40843171, 2025). "Additionally, a strong negative correlation between DLG1 mRNA levels and the expression of KDM5B was observedin PDAC tumor tissue." (PMID 38789418, 2024). "Furthermore, the in vivo study in Balb/c nude mice also showed that KDM5B silence with shRNA suppressed tumour cell proliferation (P < 0.001)." (PMID 38862740, 2024). "Furthermore, we demonstrated the reason for the inability to produce IL-8 in tumour cells, although KDM5B was present in tumour cells, which was attributed to competitive binding by a compromised tumour suppressor gene, RB1, in tumour cells." (PMID 38862740, 2024). "Furthermore, to assess the protein expression levels of KDM1A, KDM5A, and KDM5B in human tumor tissue, we conducted IHC on a tumor tissue microarray." (PMID 39239542, 2024). "Importantly, the addition of rabbit anti-SRGN antibody inhibited KDM5B up-regulation and IL-8 production induced by treatment with the CMs of tumour cells." (PMID 38862740, 2024). "KDM5B, however, has been identified as a tumor suppressor in MLLr AML and NUP98r AML, and KDM5C has also recently identified as a tumor suppressor, with a particularly strong association between KDM5C expression and long-term progression-free survival in female patients with AML." (PMID 39403928, 2024). "Histone demethylase KDM5B was found to be actively expressed in all subclusters of maECs, which could promote tumor invasion and induce immune evasion through cytosolic RNA or DNA sensing pathways and subsequent interferon-1 responses." (PMID 37487008, 2023). "Consistent with KDM5B protein expression in the PCa tumor specimens reported here, KDM5B mRNA expression was higher in both androgen dependent (LNCaP) and androgen-independent (LNCaP: C4-2, 22Rv1, PC3) cell lines as compared to the non-malignant PNT1A prostate cell line." (PMID 37152294, 2023). "Furthermore, KDM5B overexpression contributes to drug resistance in certain tumor types and induces metastasis and angiogenesis by repressing HOXA5." (PMID 38004468, 2023). "If an S1 tumor were identified before treatment, it might be possible to change its susceptibility to CPI by using an inhibitor targeting FGFR3 or KDM5B." (PMID 37105962, 2023). "However, there are conflicting studies: H3K4me3 decreases DNA damage repair; KDM5B facilitates DNA repair in tumor cells under radiation treatment; and KDM5B inhibition impairs DNA damage repair, sensitizing tumor cells to radiation." (PMID 38004468, 2023). "KDM5B regulon activity is high in the S1/Lum-E tumor subtype, in contrast to the other resistant subtype, S4/MycU, suggesting that these two subtypes may have disparate mechanisms of resistance." (PMID 37105962, 2023). "KDM5B can specifically reduce the level of histone 3 lysine 4 trimethylation (H3K4me3), thereby activating the expression of related genes and participating in biological processes such as cell differentiation, embryonic development and tumor formation." (PMID 35788877, 2022). "The KDM5B-mediated effect on tumor proliferation was then studied in vivo." (PMID 35650266, 2022). "The expression of KDM5B correlated with tumor growth and cell motility." (PMID 35326475, 2022). "They identified SETDB1 (or SETDB1 recruited by KDM5B) as a chromatin regulator that depresses tumour-intrinsic immunogenicity and mediates immune tolerance in both mice and human tumours, and SETDB1 depletion potently boosted the efficacy of ICB in mouse models." (PMID 36582533, 2022). "The expression levels of SH3BP1, KDM5B (involved in serine/threonine kinase activity pathway) and PI4KA (belongs to inositol phosphate metabolism pathway) were notably increased in cells overexpressing CPTP, and are associated with tumor progression." (PMID 35982909, 2022).
tumor (continued). "KDM5B can specifically reduce the methylation level of histone 3 lysine 4 (H3K4) without causing changes of other sites, and participate in a variety of biological processes such as embryo development, cell differentiation and tumor formation." (PMID 35788877, 2022). "Besides, KDM5B was found to be overexpressed in CRC tumor tissue compared with normal colon samples and this overexpression positively correlated with cancer progression." (PMID 32751840, 2020). "Though the role of KDM5B in tumorigenesis is not well understood, its higher expression in cancer cells may regulate the distribution of H3K4me3 near promoter regions of tumor suppressors and modulate their expression, thus affecting cancer cell proliferation." (PMID 33245716, 2020). "However, KDM5B has also been suggested as a tumor-suppressive agent in melanocytic cells through the regulation of activities of the retinoblastoma protein." (PMID 32751840, 2020). "Notably, KDM5B mRNA levels were elevated in PCa patient tumors with high tumor grade, i.e., combined Gleason Scores (GS) of 7–9." (PMID 33245716, 2020). "However, a tumor-suppressive role of KDM5B has also been reported in TNBC, partly due to its ability to bind and stabilize hypophosphorylated pRb22–24." (PMID 31776402, 2019). "In the invasion and migration assay, the inhibition of KDM5B could suppress tumor invasion significantly." (PMID 30344945, 2018). "Examples for biological heterogeneity include switching between proliferative and invasive states, variable expression of tumor-associated antigens as well as dynamic expression of CSC markers including CD133, ABCB5, NGFR or KDM5B." (PMID 29192388, 2018). "KDM5B expression was related well with tumor size, TNM stage, edmondson grade, and poor prognosis." (PMID 27974677, 2017). "Besides, silencing KDM5B significantly inhibited oral squamous cancer stem cell activity, its migration and invasion ability, potentiated the tumor-inhibitory effects for radiation therapy." (PMID 27974677, 2017). "However, in addition to serving as an oncogene, KDM5B had been shown to have tumor-suppressive activities." (PMID 27974677, 2017). "KDM5B promoted tumor sphere formation and invasion and resisted cisplatin treatment." (PMID 27974677, 2017). "Besides, increasing studies revealed that KDM5B was involved not only in tumor initiation, but also in tumor progression such as invasion and metastasis." (PMID 26911146, 2016). "To illustrate the functional importance of the binding between PHD1KDM5B and the unmodified H3K4, we tested whether the mutants could affect the expression of tumor suppressor genes compared with wild-type KDM5B." (PMID 24952722, 2014). "The data indicate that both E2F1 and E2F2 could be highly expressed in tumor tissues correlating with elevated expression of KDM5B (Spearman's rank correlation coefficient: r = 0.666 [E2F1] and r = 0.756 [E2F2], respectively)." (PMID 20226085, 2010). "Therefore, we were interested in investigating whether KDM1A, KDM5A, and KDM5B expression was correlated with the enrichment of tumor-infiltrating lymphocytes in PC." (PMID 39239542, 2024). "Moreover, a positive association was observed between increasing tumor grade and KDM5B expression, while simultaneously, a negative correlation was identified between P16 and KDM5B expression." (PMID 38769556, 2024). "Moreover, KDM5B expression is related to the tumor size, staging, and degree of differentiation." (PMID 38004468, 2023). "In contrast, KDM5B may function as a tumor suppressor in triple-negative breast cancer (TNBC)." (PMID 35805040, 2022). "Moreover, AS-8351 could inhibit tumor growth in nude mice models, indicating the antitumor effect of targeting KDM5B in EwS." (PMID 35428764, 2022). "Similarly, increased levels of KDM5B are found in HCC tumor samples and cellular models." (PMID 34200849, 2021).
tumor (continued). "However, subsequent studies have revealed increased heterogeneity of KDM5B in CM, and its expression levels have been documented to define distinct cellular states, even with antithetical effects on cellular tumor fate depending on the biological and clinical context." (PMID 34575678, 2021). "When challenged with drugs, the intrinsically slow-cycling KDM5B high expression cell state became initially enriched, whereas under persistent drug-exposure melanomas decrease KDM5B expression again to re-enter cell proliferation for long-term tumor repopulation." (PMID 34591417, 2021). "Furthermore, KDM5B was significantly more expressed in the cytoplasm of ESCC cells compared to normal mucosa and its nuclear expression was associated with histologic grade, as poorly differentiated tumours displayed significantly lower nuclear KDM5B levels." (PMID 32429269, 2020). "In all these studies, genetic or pharmacologic inhibition of KDM5B upregulates the expression of tumor suppressor genes and caused growth arrest and apoptotic cell death in cancer cells suggesting that KDM5B may mostly act as a repressor of tumor suppressor genes." (PMID 33245716, 2020). "Increased expression of KDM5A and KDM5B have previously been found to be functionally important markers of slow cycling cancer cells that are enriched upon drug exposure, whereas the pre-existing KDM5Bhigh subpopulation was also found to be essential for continuous tumor growth in melanoma." (PMID 29192388, 2018). "We also identified six UPRs unique to CPA-treated B16F10 tumors vs. GL261(B6) tumors that promote tumor cell survival or tissue repair and may contribute to B16F10 tumor unresponsiveness: activated UPRs KDM5B, RBL2 and SPARC; and inhibited UPRs FOXM1, CD24 and CSF2)." (PMID 27515027, 2016). "We first examined the correlation of expression between KDM5B and all EBV genes, utilizing transcriptome data from 113 NPC tumor biopsy samples." (PMID 40059116, 2025). "Expression analysis of the excised tumor tissues revealed that compared to the sh-NC group, the sh-RBM15 group exhibited decreased expression of RBM15, KDM5B, and KCNQ1OT1, and increased expression of FER1L4 (p < 0.01)." (PMID 39039611, 2024). "Here, we showed that lysine-specific demethylase 5B (KDM5B) was overexpressed and correlates with tumor progression and cisplatin resistance in patients with NPC." (PMID 38287116, 2024). "In contrast, the combination of GEM with CA3 reduced tumor growth and restored sensitivity to GEM therapy in KDM5B-overexpression tumors." (PMID 38789418, 2024). "The examination indicated the hub genes in tumor samples, including GAGE2A, GAGE1, MAGEA9, CTAG1A, CTAG1B, and MAGEA1; and the hub genes in healthy ovarian tissue samples, including SPA17, MAGEC1, KDM5B, SSX4, and MAGEA9." (PMID 37835834, 2023). "Interaction among TFAP2C, c-Myc and lysine demethylase 5B (KDM5B) can form a protein complex that promotes cell cycle progression by transcriptionally inhibiting P21 expression, consequently resulting in tumor growth." (PMID 37291585, 2023). "KDM5B overexpression decreases CCL14 and activates the Wnt/β-catenin pathway, promoting tumor progression." (PMID 38004468, 2023). "KDM5B demethylates H3K4 and acts as a transcriptional repressor on tumor suppressor genes, leading to their inactivation." (PMID 38004468, 2023). "By enhancing the SUMOylation of KDM5B mediated by SUMO3 and responsible for SUMO E3 ligase PIAS4, hypoxia promotes the stability of KDM5B, which is conducive to the response of tumor cells to anoxic environment." (PMID 37777749, 2023). "Moreover, we found that AS-8351 inhibited the growth of EwS tumor xenografts without causing side effects in the mice, suggesting that epigenetic drug targeting KDM5B could be an effective anti-tumor agent for EwS treatment." (PMID 35428764, 2022). "The overexpression of KDM5B also results in a reduction in cancer stem cell frequency in TNBC cell lines, suggesting tumor-suppressive roles of KDM5B in TNBC." (PMID 35805040, 2022).
tumor (continued). "In HNSCC HPV+, the values of KDM5B are inversely related to those of STING, to CXCL10 (one of the interferon-induced chemokines that promotes inflammatory infiltrate in the tumor microenvironment), and to the amount of CD8+ infiltrate." (PMID 36499710, 2022). "To investigate the role of KDM5B in EwS, we investigated KDM5B mRNA expression levels in GSE17674 dataset containing 44 tumor tissues from EwS patients and 14 normal tissues from skeletal muscle." (PMID 35428764, 2022). "JARID1B (also termed KDM5B) is a member of the JMJC histone demethylase family and was shown to be involved in tumor progression and metastasis, including GC." (PMID 34778074, 2021). "Previous studies have shown that miR‐194 inhibited tumor progression by downregulating FOXM1, RBX1, and KDM5B." (PMID 33605558, 2021). "KDM5B (also known as PLU1 or JARID1B), demethylates lysine 4 of histone 3 (H3K4), and acts as a transcriptional repressor on certain tumor suppressor genes, thus converting it into the transcriptionally inactive state." (PMID 32751840, 2020). "Besides, KDM5B could epigenetically repress the expression of tumor suppressive let-7e." (PMID 27974677, 2017). "Meanwhile, KDM5B knockdown increased G1 phase of MCF7 cells and retarded in vitro growth, colony formation in soft-agar and in vivo tumor formation." (PMID 27974677, 2017). "Our previous publications have demonstrated that IKZF1 exerts anti-tumor effects by regulating the expression of its target genes such as c-Myc, PI3KCD, KDM5B, etc.." (PMID 27391346, 2016). "KDM5B is frequently up-regulated in HCC specimens compared with adjacent normal tissues and its expression level was significantly correlated with tumor size, TNM stage, and Edmondson grade." (PMID 26911146, 2016). "Notably, we observed a unique positive correlation between KDM5B and EBNA1 in NPC tumor samples, collaborating with the concurrent upregulation of KDM5B and EBNA1 in EBV-positive or EBV-infected NPC and GC cells." (PMID 40059116, 2025). "Moreover, in vivo xenograft models clearly showed that PLK2 overexpression significantly curtailed the tumor growth boosted in CNE2-EBV and AGS-EBV cells due to KDM5B overexpression." (PMID 40059116, 2025). "RT-qPCR analyses in both EBV-negative and -positive epithelial tumor cells, as well as those cells with KDM5B knockdown or overexpression, pinpointed PLK2 as the primary target with the most significant alterations affected by KDM5B." (PMID 40059116, 2025). "Compared with the sh-NC group, the tumor volume and weight were reduced in the sh-HOXC-AS3 group (p < 0.01), the positive rate of Ki67 was declined (p < 0.01), and the expression levels of lncRNA HOXC-AS3 and KDM5B were declined (p < 0.01)." (PMID 38842683, 2024). "Besides this, inhibiting KDM5B induces HEXIM1 (tumor suppressor) expression, leading to the inhibition of tumor cell proliferation and the prevention of metastasis formation." (PMID 38004468, 2023). "This gene, which has tumor suppressor activity in MCF7 cells, recruits KDM5B to the promoter." (PMID 36697763, 2023).
tumor (continued). "A recent analysis characterized the tumor and immune microenvironment incorporating digital spatial profiling in pre- and post-treatment tumors from the PURE01 to identify the histone demethylase KDM5B as a repressor of tumor-immune signaling pathways." (PMID 37296985, 2023). "Furthermore, the literature suggests that KDM5B activates the PI3K/AKT signaling pathway, while reducing KDM5B expression decreases AKT signaling, resulting in decreased tumor cell proliferation." (PMID 38004468, 2023). "Our study found that KDM5B activates the EMT signaling pathway, which leads to the formation of secondary metastatic lesions by promoting cell motility/invasion and chemoresistance of tumor cells." (PMID 37880235, 2023). "Lysine Demethylase 5B (KDM5B) recruits SETDB1 to inhibit endogenous retroelements in a demethylase-independent manner, thereby inhibiting the cGAS-STING pathway and type-I interferon response, which contributes to tumor growth and immune memory inhibition." (PMID 38057834, 2023). "KDM5B expression was observed as expected in the nucleus, but also in the cytoplasm of non-malignant and tumor specimens." (PMID 37152294, 2023). "Expression of KDM5B showed positive correlation with AR in non-malignant (R = 0.72, p < 0.01) and tumor specimens (R = 0.44, p < 0.01)." (PMID 37152294, 2023). "Moreover, the list of KDM5B-NTT-induced genes is highly enriched in genes belonging to interferon-alpha and gamma response and inflammation, which have a primary role in tumor progression and regression." (PMID 36697763, 2023). "Besides, the expression of KDM5B, miR‐448, YTHDF3 and ITGA6 in mouse tumour tissues was measured by RT‐qPCR; the results revealed that up‐regulation of KDM5B reduced miR‐448 expression, while up‐regulating KDM5B, YTHDF3 and ITGA6 expression." (PMID 33829656, 2021). "Collectively, KDM5B could activate the YTHDF3/ITGA6 pathway to enhance the proliferation and growth of tumour cells by inhibiting the expression of miR‐448 in HCC, eventually leading to the occurrence of HCC." (PMID 33829656, 2021). "However, in the first set of results, HDM genes (KDM1A, KDM5B, KDM6A and KDM7C) were mostly overexpressed in tumour tissue comparatively to normal oesophageal epithelium." (PMID 32429269, 2020). "On the other hand, increased cellularity in Kdm5b-deleted mouse prostate implies that Kdm5b might demethylate the H3K4 in the promoter/enhancer regions of tumor-promoting genes and keep them in a repressed state during normal prostate development." (PMID 33245716, 2020). "Despite recent discoveries in the area about functions of KDM5B during various tumor progressions, we still do not fully know the mechanisms." (PMID 27974677, 2017). "In some highly metastatic types such as triple negative breast cancer (TNBC), KDM5B exhibited increased expression levels through its downstream target MALAT1, a long non-coding RNA (lncRNA), to increase tumor migration and invasion, leading to a poor survival in TNBC." (PMID 27974677, 2017). "Significant correlations were found between KDM5B expression and tumor size, TNM stage, and Edmondson grade, suggesting that KDM5B might have a stimulatory role in the progression of HCC." (PMID 26911146, 2016). "In this study we show that the microRNA hsa-miR-137 (miR137) tumor suppressor regulates expression of an extended network of transcriptional coregulators including KDM1A/LSD1/AOF1, KDM2A/JHDM1A/FBXL11, KDM4A/JMJD2A, KDM5B JARID1B/PLU1, KDM7A/JHDM1D/PHF8, MED1/TRAP220/DRIP205 and NCoA2/SRC2/TIF2." (PMID 26461474, 2015). "Microarray data indicated significantly higher levels of KDM5B expression in many types of tumor tissues compared to corresponding non-neoplastic tissues." (PMID 20226085, 2010). "Furthermore, KDM5B knockdown significantly inhibited NPC cell proliferation, while the suppressive effects were largely rescued by PLK2 knockdown, suggesting that PLK2 is a major downstream mediator of KDM5B-induced tumor progression." (PMID 40059116, 2025).